GCSH (glycine cleavage system protein H)
Description:
The glycine cleavage system catalyzes the degradation of glycine. The H protein (GCSH) shuttles the methylamine group of glycine from the P protein (GLDC) to the T protein (GCST). Has a pivotal role in the lipoylation of enzymes involved in cellular energetics such as the mitochondrial dihydrolipoyllysine-residue acetyltransferase component of pyruvate dehydrogenase complex (DLAT), and the mitochondrial dihydrolipoyllysine-residue succinyltransferase component of 2-oxoglutarate dehydrogenase complex (DLST).
Synonyms: GCE; MMDS7; NKH
Tractability: PROTAC: its protein half-life has been measured.
Gene: Protein-coding gene on chromosome 16 (81,081,945 to 81,096,406, reverse strand). Ensembl gene ENSG00000140905.
Subcellular location: Mitochondrion
Subcellular location (Human Protein Atlas): Vesicles
Pathways (Reactome):
Metabolism: Glycine degradation
Metabolism of proteins: Protein lipoylation
Gene Ontology:
Molecular function: protein binding
Biological process: glycine decarboxylation via glycine cleavage system
Cellular component: mitochondrion; glycine cleavage complex; mitochondrial matrix
Genetic constraint (gnomAD): Loss-of-function variants: 1 observed, 2.77 expected, observed/expected ratio (o/e) 0.36, 90% interval 0.12 to 1.54. That is too few expected variants to judge how well the gene tolerates losing a copy. Missense variants: 56 observed, 37.47 expected, observed/expected ratio (o/e) 1.49, 90% interval 1.2 to 1.84. Synonymous variants: 22 observed, 14.72 expected, observed/expected ratio (o/e) 1.49, 90% interval 1.05 to 1.91.
Gene-disease validity (ClinGen):
ClinGen rates the evidence that GCSH causes each of these diseases.
multiple mitochondrial dysfunctions syndrome 7 (autosomal recessive): Definitive.
Homologues: Orthologues: chimpanzee GCSH (99% identical), guinea pig GCSH (85% identical), rat Gcsh (85% identical), mouse Gcsh (80% identical), rat Gcshl1 (77% identical), rat AABR07067762.1 (65% identical), tropical clawed frog gcsh (65% identical), Drosophila melanogaster ppl (46% identical), Caenorhabditis elegans gcsh-2 (39% identical), Caenorhabditis elegans gcsh-1 (35% identical).
Diseases named in the same sentence as GCSH in open-access papers:
GCSH is named in the same sentence as 37 diseases in open-access papers, as found by Europe PMC text mining. Sharing a sentence is not in itself a finding about the gene and the disease. The quoted sentences say what the papers report.
breast carcinoma (12 papers, 2018 to 2026). "It has also been reported that GCSH is associated with the incidence of breast cancer, colorectal cancer, and papillary thyroid cancer." (PMID 36249422, 2022). "Our initial analysis revealed a GCSH-overexpression of the protein-coding transcript variant 1 (Tv1) in breast cancer cells and tissue." (PMID 30337557, 2018). "Secondly, due to the identification of a second transcript variant (Tv*), which is downregulated in all tested breast cancer cell lines, we hypothesized that Tv* could be important for the regulation of the cellular GCSH content, perhaps via antisense repression." (PMID 30337557, 2018). "Currently, there are very few studies on the correlation between GCSH and cancer, and only one article has described the correlation between GCSH and breast cancer." (PMID 37697421, 2023). "It has been reported that GCSH is a vital factor in maintaining the cellular metabolic status and viability, indicating that it is a critical biomarker in breast cancer cells." (PMID 36902801, 2023). "The study reported that the level of GCSH expression in breast cancer tissue was higher than that in normal breast tissue, which was similar to our results." (PMID 37697421, 2023). "Our first result confirmed that the GCSH protein is overexpressed in breast cancer tissue and breast cancer cells." (PMID 30337557, 2018). "All three breast cancer cell lines displayed approximately 10-fold higher GCSH protein expression as well as significantly boosted PCNA contents and moderate lowered ß-actin levels." (PMID 30337557, 2018). "This fundamental finding raises the question, if higher GCSH protein amounts have an impact on the proliferation of breast cancer cells?" (PMID 30337557, 2018). "GCSH (glycine cleavage system protein H) is an enzymatically inactive cofactor of the other three glycine cleavage system enzymes and was up-regulated in thyroid cancer, lung cancer, breast cancer tissues." (PMID 36902801, 2023). "The antisense regulation of GCSH can determine the viability of breast cancer cells." (PMID 37007145, 2023). "Intracellular GCSH content is a critical factor in determining cellular metabolic status and viability, including tumorigenesis, and it has been shown that GCSH is an effective tumor marker in breast cancer." (PMID 36195876, 2022). "Indeed, increased GCSH expression levels of the breast cancer cell lines MCF-7 and BT-20 were also calculated on transcript and protein levels, with MDA-MB-231 as an exception." (PMID 30337557, 2018). "Similar results were obtained by GCSH-immunofluorescence labeling of breast cancer cell lines." (PMID 30337557, 2018). "In contrast, the GCSH protein could be detected equally distributed in the whole mammary carcinoma tissue, with an expression score ranging from 2+ to 3+." (PMID 30337557, 2018). "Collectively, our results suggest that the cellular GCSH content is a key factor that determines the metabolic state and viability of cells, including tumorigenesis, and thus is a potent tumor marker for highly proliferative breast cancers." (PMID 30337557, 2018). "A GCSH-overexpression could be confirmed for the breast cancer cell lines MCF-7 and BT-20." (PMID 30337557, 2018). "Hence, breast cancer cells were next transfected with GCSH-Tv*-loaded nanoparticles." (PMID 30337557, 2018). "In the GSE145548 cohort, knockdown of ATF2 in breast cancer cells MCF7 resulted in the dramatic change of cuproptosis regulators (DLST, GCSH, PDHA1, LIPT1 and DLD)." (PMID 36733399, 2022). "However, we here demonstrate for the first time that additional GCSH, which very likely results in higher overall GCS activity, strengthens the viability of the breast cancer cells and therefore forces tumorigenesis." (PMID 30337557, 2018).
glycine encephalopathy (6 papers, 2014 to 2024). Glycine encephalopathy (GE) is an inborn error of glycine metabolism characterized by accumulation of glycine in body fluids and tissues, including the brain, resulting in neurometabolic symptoms of variable severity. "Here, we report six patients with biallelic pathogenic variants in GCSH and a broad clinical spectrum ranging from neonatal fatal glycine encephalopathy to an attenuated phenotype of developmental delay, behavioral problems, limited epilepsy and variable movement problems." (PMID 36190515, 2023). "Nonketotic hyperglycinemia (NKH) is a rare, autosomal recessive metabolic disorder usually associated with mutations in genes AMT, GLDC or GCSH involved in the glycine cleavage complex." (PMID 39323869, 2024). "Glycine encephalopathy is associated with mutation in AMT, GLDC, and GCSH genes." (PMID 25029527, 2014). "In addition, approximately 5% of patients with enzyme-proven glycine encephalopathy do not have a pathogenic variant in GLDC, AMT or GCSH genes; these cases therefore represent a variant form of NKH." (PMID 29304759, 2018).
colorectal cancer (4 papers, 2022 to 2025). A primary or metastatic malignant neoplasm that affects the colon or rectum. "It was found that the mutation frequency of each regulator is relatively low, of which ATP7A showed the highest mutation rate, followed by ATP7B and LIPT1, while FDX1, CDKN2A, SLC31A1, and GCSH showed no mutation in all colorectal cancer tissues." (PMID 36248908, 2022). "The study revealed that, compared to normal tissues, genes FDX1, DLD, DBT, DLST, and DLAT were significantly downregulated in colorectal cancer tissues, while LIPT1, GCSH, and ATP7B genes were upregulated." (PMID 40276654, 2025). "On the TCGA colorectal cancer dataset, RTCpredictor re-identified five out of eleven known read-throughs (CTSD-IFITM10, GCSH-C16orf46, METTL21B-TSFM, SLC2A11-MIF and TRIM2-MND1)." (PMID 38796690, 2024).
glioma (4 papers, 2021 to 2024). A benign or malignant brain and spinal cord tumor that arises from glial cells (astrocytes, oligodendrocytes, ependymal cells). "Furthermore, Cox regression analysis in the TCGA database showed that FDX1, LIPT1, DLD, DLAT, SLC31A1, ATP7A, and DLST might be risk factors; however, LIAS, ATP7B, and GCSH were significant preventive factors for gliomas." (PMID 37515314, 2023). "The greatest differences appear between glioblastoma and other gliomas (particularly in relation to tumor grade G4 vs. G3/G2), where GCSH and PLEK2 can be used to distinguish them since they exhibit opposite expression profiles in this regard." (PMID 34204789, 2021). "In addition, GCSH expression is clearly lowered with increasing glioma grade, while that of PLEK2 and RRM2 is clearly elevated; therefore, GCSH does not fit the premise of targeted therapy, i.e., biological pathway inhibition." (PMID 34204789, 2021). "Here, our study indicates that GCSH expression dramatically declines with increasing glioma grade." (PMID 34204789, 2021). "Further investigation is needed pertaining to PLEK2 and GCSH to analyze their prognostic accuracy and ability to differentiate between GBM versus alternative gliomas." (PMID 36837779, 2023). "Together with the already described glioma biomarker, RRM2, we considered PLEK2 and GCSH as a novel WWOX-dependent biomarker triad of glioblastoma, whose subsequent investigation is advisable." (PMID 34204789, 2021). "Regarding GCSH, targeted therapy is not justified as its expression decreases with increasing glioma grade; hence, it is not a therapeutic biomarker." (PMID 34204789, 2021).
cholangiocarcinoma (2 papers, 2024 to 2025). A carcinoma that arises from the intrahepatic biliary tree (intrahepatic cholangiocarcinoma) or from the junction, or adjacent to the junction, of the right and left hepatic ducts (hilar cholangiocarcinoma). "The high expression of GCSH (γ-glutamylcysteine synthetase) has been confirmed to be associated with poor prognosis in endometrial cancer and cholangiocarcinoma patients." (PMID 40276654, 2025).
epilepsy (2 papers, 2019 to 2023). A brain disorder characterized by episodes of abnormally increased neuronal discharge resulting in transient episodes of sensory or motor neurological dysfunction, or psychic dysfunction. "GCSH (Glycine Cleavage System Protein H): Glycine encephalopathy (hypotonia, delayed psychomotor development, and epilepsy)." (PMID 31031802, 2019).
amino acid metabolic disorder (1 paper, 2021). "According to the modern algorithm developed by the Alliance of Genome Resources, the “automated description” indicates that GCSH is biomarker of amino acid metabolic disorder, which is a known abnormality in GBM." (PMID 34204789, 2021).
astrocytoma (1 paper, 2021). "As GCSH was the gene that can distinguish G4 from G3 brain tumors, we speculate this occurs (beyond IDH wild-type GBM development) over the transformation from G3 astrocytoma to G4 glioblastoma." (PMID 34204789, 2021).
atherosclerosis (1 paper, 2024). A disease characterized by the build-up of fatty material and calcium deposition in the arterial wall resulting in partial or complete occlusion of the arterial lumen. "It has previously been shown that in mouse macrophages, ERK1/2 upregulated the expression of GCSH, thereby promoting the production of AGEs, which are involved in the pathogenesis of diabetes-related atherosclerosis." (PMID 38883603, 2024).
chronic apical periodontitis (1 paper, 2025). Chronic form of periapical periodontitis. "Among these, four CRGs were found to be down-regulated in chronic apical periodontitis (CAP), namely Nuclear Factor Erythroid 2-Related Factor 2 (NFE2L2), Dihydrolipoamide S-Succinyltransferase (DLST), Solute Carrier Family 25 Member (SLC25A3), and Glycine Cleavage H Protein (GCSH)." (PMID 40909264, 2025).
gastric cancer (1 paper, 2024). A primary or metastatic malignant neoplasm involving the stomach. "We conducted molecular experiments to validate our findings, and the results of Western blot analysis revealed notable disparities in the expression levels of FDX1, LIAS, DLAT, DLST, GCSH, PDHB and PDHA1 in gastric cancer cells between the CSRS‐Low (AGS) and CSRS‐High (HGC‐27) subtypes." (PMID 38898987, 2024).
liver cancer (1 paper, 2023). An epithelial or non-epithelial malignant neoplasm that arises from the liver. "Moreover, we used the Kaplan–Meier plotter tool to analyze the overall survival of patients with liver cancer based on the expression of the FDX1, DBT, GCSH, SLC31A1, and DLAT genes." (PMID 37763758, 2023).
lung adenocarcinoma (1 paper, 2024). A carcinoma that arises from the lung and is characterized by the presence of malignant glandular epithelial cells. "A recent study demonstrated the upregulation of seven genes (DLAT, DLD, glycine cleavage system protein H (a protein-coding gene, GCSH), LIAS, LIPT1, PDHA1, and PDHB) in lung adenocarcinoma patients." (PMID 39068453, 2024).
pulmonary diseases (1 paper, 2023). "However, GCSH's role in the development of pulmonary diseases has not been fully interpreted." (PMID 37279744, 2023).
sarcoma (1 paper, 2024). A usually aggressive malignant neoplasm of the soft tissue or bone. "In terms of gene signatures, an immune-related five-gene signature based on MYBL2, FBN2, TSPAN7, GCSH, and DDX39B is a prognostic biomarker for sarcoma patients." (PMID 38240704, 2024).
tumor (23 papers, 2018 to 2026). "The association patterns of NFE2L2 and GCSH in the tumor cell region and immune cell region of NPC are different when Jab1 is lowly expressed." (PMID 36618352, 2022). "Nine CRGs were differentially expressed between tumor and normal tissues, among which NFE2L2, SLC31A1, FDX1, DLD, DLAT, and DLST were lowly expressed in tumor tissues, and ATP7B, CDKN2A, and GCSH were highly expressed in tumor tissues (p<0.05)." (PMID 37205181, 2023). "We further studied the relative expression of core cuprotosis risk genes NFE2L2, NLRP3, SLC31A1, and GCSH in GC STAD and confirmed that NFE2L2 has low expression in STAD tumor tissue, while SLC31A1 and GCSH genes were highly expressed in STAD tumor tissue." (PMID 36249422, 2022). "Combining the outcomes of these two analytical approaches, we hypothesize that GCSH potentially augments tumor malignancy through the JAK-STAT signaling pathway in CCA." (PMID 38370386, 2024). "The other five CRGs, including FDX1, SLC31A1, LIPT2, PDHA1 and GCSH, did not have any mutations in tumor samples." (PMID 36479114, 2022). "Gene expression profiling showed that SLC31A1, LIPT2, CDKN2A, and GCSH expression was increased in tumor tissues, while NFE2L2, NLRP3, ATP7A, DLD, MTF1, and DLST expression was decreased in tumor tissues compared with normal tissues." (PMID 37065485, 2023). "Among them, 7 genes (DLAT, DLD, GCSH, LIAS, LIPT1, PDHA1, and PDHB) were upmodulated, whereas 3 genes (ATP7B, FDX1, and SLC31A1) were downmodulated in the tumor group in contrast with the normal group (p < 0.05)." (PMID 36046242, 2022). "We found that the expression of GCSH and DLAT was much higher in tumor tissues than in normal tissues in LUAD." (PMID 36353226, 2022). "With low expression of Jab1, NFE2L2 was negatively correlated with GCSH expression in tumor cell enriched regions, while NFE2L2 was positively correlated with GCSH expression in immune cell enriched regions." (PMID 36618352, 2022). "The results showed that, in tumor samples, ATP7B, PDHA1, and SLC31A1 were significantly upregulated compared with normal tissues, whereas ATP7A, DLST, GCSH, LIAS, and LIPT1 were significantly downregulated." (PMID 36567939, 2022). "GCSH + macrophages exhibited extensive interactions with T cells via pathways such as MIF-CD74-CXCR4 and LGALS9-CD45, contributing to an immunosuppressive, tumor-promoting microenvironment." (PMID 42111497, 2026). "In tumor cell-enriched region, the expression of COPS5, DLAT, DLD, FDX1, NFE2L2, PDHA1 and PDHB in the high score group is higher than that in the low score group, while the opposite is true for DLST, GCSH and LIPT2 (P <0.05)." (PMID 36618352, 2022). "So far, no GCSH expression studies in correlation with tumor progression are available." (PMID 30337557, 2018). "Additionally, we identified a negative correlation between GCSH expression and p-STAT3 in the tumor tissues of CCA patients using IHC." (PMID 38370386, 2024).
cancer (10 papers, 2018 to 2025). A tumor composed of atypical neoplastic, often pleomorphic cells that invade other tissues. "The transcriptional levels of DLAT, FDX1, DBT, DLD, PDHB, and GCSH negatively correlate with methylation in part of tumors (> 7 cancer types)." (PMID 36209249, 2022). "Regarding phenotype comparisons for which these genes were representative, both GCSH and PLEK2 distinguished cancer grades: GCSH expression was lower in G4 than in G3, while PLEK2 was higher in G4 compared to G2." (PMID 34204789, 2021). "GCSH was lower expression in 24 cancers, except for BLCA, HNSC, READ, and TGCT." (PMID 38671021, 2024). "Interestingly, UHRF1 was indicated as a universal cancer biomarker, while GCSH seems to be newly observed." (PMID 34204789, 2021). "However, no cancer associated studies are available for the Glycine Cleavage System Protein H (GCSH) to date." (PMID 30337557, 2018). "In Cuproptosis-related genes, SPC25 was positively correlated with GCSH, CDKN2A, PDHB, PDHA1, DLAT, DLD, and SLC31A1 of pan-cancer." (PMID 38605119, 2024). "In contrast, eight regulators (PDHA1, ATP7A, LIPT1, LIPT2, GLS, ATP7B, GCSH, and CDKN2A) were upregulated in cancer tissues." (PMID 36672336, 2023). "Our study showed that MRPL13 and its associated genes were significantly correlated with cuproptosis-related genes across cancers, with the most significant ones being FDX1, GCSH, DLST, and DLD." (PMID 37827692, 2023). "The three genes (GCSH, LIPT1, CDKN2A) that we used to construct cuproptosis-related prognostic models played important roles in the progression of various types of cancer." (PMID 36195876, 2022).
infection (1 paper, 2023). The state of being infected such as from the introduction of a foreign agent such as serum, vaccine, antigenic substance or organism. "We hypothesize that the upregulation of GCSH in the SCAP group may be due to the increased need for energy during infection and inflammation." (PMID 37279744, 2023).
GCSH also shares sentences with these, for which no sentence is quoted: papillary thyroid cancer (2 papers); triple-negative breast carcinoma (2); arrhythmogenic right ventricular cardiomyopathy (1); Azoospermia (1); biotinidase deficiency (1); bladder cancer (1); brain tumors (1); COVID-19 (1); diabetes (1); Encephalopathy (1); endometrial cancer (1); glioblastoma (1); lung carcinoma (1); metabolic disorder (1); oligospermia (1); psoriasis (1); rheumatic diseases (1); soft tissue sarcoma (1); thyroid cancer (1).